CD24 (CD24 molecule)
Diseases named in the same sentence as CD24 in open-access papers (continued):
Sharing a sentence is not in itself a finding about the gene and the disease.
breast cancer (continued). "According to existing literature, CD44 is highly expressed in stem cells from breast cancer, gastric cancer, and oral squamous cell carcinoma, while CD24 is typically expressed at lower levels." (PMID 39247186, 2024). "One predictive predictor for individuals with early and intermediate-stage breast cancer is the positive expression of CD24 in CTCs, particularly in mixed-CTCs." (PMID 38279998, 2024). "100% tumor incidence was observed in the mice transplanted with CD24+‐breast cancer cells and CD24−/CD44+‐breast CSCs." (PMID 38522013, 2024). "Decreased CD24 expression in breast cancer cells correlates with resistance to radiation and the management of oxidative stress, in addition to acquiring a hybrid E/M phenotype." (PMID 39124569, 2024). "This means that CD38 on IgD+ CD24‐ plays a key mediating role in the link between breast cancer and M funiformis." (PMID 39654239, 2024). "The expression of IMP3 in CD44+CD24‐ESA+ cell clusters in breast cancer tissue was significantly upregulated." (PMID 38358034, 2024). "It is noted that the feasibility of EV’s CD24 and EpCAM to detect breast cancer needs to be validated with a larger cohort and with other molecular subtypes (i.e., hormone-positive and triple-negative breast cancer)." (PMID 39513819, 2024). "Breast cancer spheroids enriched with CD44+/CD24- cells grew tumors and targeting these CSCs with niclosamide inhibited spheroid formation, induced apoptosis, and inhibited tumor growth in mice." (PMID 38737455, 2024). "The results show that CD24 is highly expressed in breast cancer tissues and cell lines, and knockdown of CD24 in vivo and in vitro can inhibit the proliferation, migration and invasion of BC cells." (PMID 38914670, 2024). "In contrast, a significant increase in the expression levels of human CD24, as well as the epithelial genes such as E‐Cadherin, EpCAM, and Mucin, was observed in tumor tissues of mice xenotransplanted with CD24+‐breast cancer cells." (PMID 38522013, 2024). "TNBCs, the basal subtype of breast cancer, which is highly metastatic due to the presence of CD24−/CD44+‐breast CSCs, often express epidermal growth factor receptor (EGFR) in high levels, which serve as a biomarker." (PMID 38522013, 2024). "Compound 1e potentiated the doxorubicin‐mediated inhibitory effect on proliferation, migration, in‐vitro tumorigenesis capacity, and induction of apoptosis in MDA‐MB‐231 cells, and in the sorted CD24+‐breast cancer cells and CD24−/CD44+‐breast CSC populations." (PMID 38522013, 2024). "To further investigate this relationship, we analyzed publicly available microRNA profiles of MCF-7 breast cancer cells sorted for a surface marker phenotype commonly associated with increased stemness, CD44+/CD24–/low/ESA+." (PMID 39189967, 2024). "Utilizing DISVT with our machine learning-assisted image analysis platform and pilot human subjects, we demonstrate that EV’s CD24 and EpCAM can be used as biomarkers to detect breast cancer (HER2-positive) at Stages II, III, and IV." (PMID 39513819, 2024). "MCF-7-derived breast cancer stem cells (CD24−/CD44+) were inoculated at a concentration of 5 × 105 cells/60 μL per gel in three replicates, and cell matrices were incubated at 37°C and 5% CO2." (PMID 38910198, 2024). "Immunohistochemical analysis of the tumor tissue sections with antibodies (Table ST3) revealed a significant increase in the colocalization of GFP and CD44 in the CD24−/CD44+‐breast CSC as compared with the CD24+‐breast cancer cell xenotransplanted groups." (PMID 38522013, 2024). "Another study showed that breast cancer cells with high ALDH activity or high CD44 with low CD24 expressed high levels of type I tyrosine kinase like orphan receptor ROR1 and had greater capacity to form spheroids." (PMID 38737455, 2024). "There were minimal quantity CD44+CD24- stem CTCs expressing integrin β4+ in peripheral blood of breast cancer patients." (PMID 38250718, 2024).
breast cancer (continued). "Considerable attention has shifted toward tumor cells expressing CD24, which hold prognostic significance in breast cancer." (PMID 38806508, 2024). "In this context, it was investigated how CD24−/CD44+ breast cancer stem cells would respond to relevant drug applications in 3D culture conditions rather than monolayer culture." (PMID 38910198, 2024). "In an independent study, sera-derived exosomes from breast cancer patients were used to characterize CD24 and EpCAM as markers for exosomes." (PMID 37629204, 2023). "The induction of EMT in immortalized, nontumorigenic human mammary epithelial cells resulted in acquisition of the CD44+/CD24– phenotype, a characteristic of breast cancer stem-like cells (CSC)." (PMID 37377604, 2023). "CSCs derived from breast cancer cells with CD44+/CD24 low/− phenotype have the ability of heterogeneous differentiation, initiating diverse tumors and forming mammospheres." (PMID 36835085, 2023). "We ascertained that CD24 expression was up-regulated in breast cancer cells compared with normal breast epithelial cells." (PMID 37842046, 2023). "These dual antibody-conjugated nanoreactors demonstrate potential for checkpoint blockade immunotherapy (CBIT) by effectively targeting and blocking PD-L1 and CD24 proteins present on breast cancer cells, specifically TNBC cells." (PMID 37875918, 2023). "The CD24−/CD44+ phenotype in the cell population is commonly used to characterize CSCs in breast cancer." (PMID 37370134, 2023). "The JAK2/STAT3 signaling pathway is required for growth of CD44(+) CD24(−) stem cell-like breast cancer cells, particularly in basal-like breast cancers and is independently associated with breast cancer metastasis and poor prognosis." (PMID 36635351, 2023). "CD24 expression was detected in human breast cancer cell lines, and the potency of its expression correlated with breast tumor grade." (PMID 37894750, 2023). "Lineage −CD44+CD24− tumor cells isolated from breast cancer patients are enriched for cancer stem cells." (PMID 37759462, 2023). "Another evidence supporting that Src as a CD24-mediator comes from a recent study showing that CD24 interacts with and promotes the activity of c-Src within lipid-rafts in breast cancer cells." (PMID 37919766, 2023). "In another study, it was shown that inhibition of autophagy by knockdown of ATG7 or BECN1 modified the CD44+/CD24low/- (stem cell phenotype) population of breast cancer cells by regulating CD24 and IL-6 secretion." (PMID 37886168, 2023). "Breast cancer stem-like cells (BCSLCs) were isolated by sorting CD44+CD24- cells from suspension cultured breast cancer (BC) spheroids." (PMID 36923432, 2023). "We confirmed the strong expression of CD24 in breast cancer through qPCR and IHC, which is consistent with previous reports." (PMID 37842046, 2023). "first reported breast cancer stem cells (BCSCs) with specific markers (EpCAM/CD44+/CD24-/low) capable of initiating tumorigenesis in vivo." (PMID 37324011, 2023). "In the current study, we detected the CD44+/CD24- subpopulation cells from breast cancer cells, and confirmed that miR-1275 plays a pivotal role in decreasing chemoresistance by reducing the properties of CSCs." (PMID 36594100, 2023). "CD24 overexpression in ovarian and breast cancer cells acts as an antiphagocytic signal by interacting with Siglec-10." (PMID 37894750, 2023). "Single-chain variable fragments (scFvs) selected from a comprehensive RNA library of lymphocytes from breast cancer patients showed excellent selectivity for CD24 and CD44 when combined with epirubicin." (PMID 37846296, 2023). "The surface expression of CD44+ high; CD24− low cells has been considered a stem population marker of breast cancers." (PMID 37507768, 2023). "A pioneering study indicated that CD44 + /CD24- cells can be recognized as prospective breast cancer stem cells." (PMID 37919766, 2023).
breast cancer (continued). "A pro-oncogenic role for miR-31 in breast cancer has been proposed, since it was found enriched in mammary stem cells (MaSC) and breast tumors, and appears to be essential for maintaining mammary tumor stem cells (CD24+/CD90+) in the MMTV-PyVT mice model." (PMID 37374142, 2023). "Among them was CD24, a marker of pancreatic cancer stem cells and regulator of drug resistance in breast cancer cell lines, which validated our screening platform." (PMID 37327088, 2023). "Microarray analysis of breast cancer tumors showed that the gene expression profile of the CD44+/CD24– fraction resembled that of stem cell–like cells, and this subpopulation was able to form mammospheres in vitro." (PMID 37377604, 2023). "The overexpression of Slug in MCF-10A and MCF-7 breast cancer cells (CD44-/CD24+) generates a subpopulation of cancer stem cells with a CD44+/CD24+ phenotype showing an enhanced mammosphere-forming ability." (PMID 37835592, 2023). "Several groups have used in vitro models to successfully propagate breast cancer CTCs and study tumor spheres after the loss of cell-matrix interactions, which revealed an increase in the stem-like CD44+CD24− population." (PMID 36979915, 2023). "CD44+/CD24− breast cancer cells have also been shown to upregulate NF-κB compared to CD44−/CD24+ breast cancer cells." (PMID 37370720, 2023). "Nonetheless, a study revealed that CD24 in MDA-MB-231 breast cancer cells limits the CXCR4 localisation in membrane lipid rafts, thereby controlling its downstream signalling changes." (PMID 38137380, 2023). "In breast cancer TGFB-RII expression is inversely correlated with ER expression and the CD44+/CD24- cell phenotype has been associated with ER-/TGFB-RII+ patients." (PMID 36831452, 2023). "Recent studies have confirmed CD44 + /CD24- phenotype in breast cancer patients was negatively correlated with postoperative DFS and OS." (PMID 36964570, 2023). "The results showed that crassolide significantly increased ICD and slightly decreased the expression level of CD24 on the surface of murine mammary carcinoma cells." (PMID 37103364, 2023). "In vitro results demonstrated that ASR490 significantly inhibited BCSCs (ALDH+ and CD44+/CD24–) and breast cancer (BC) growth at nM concentrations, and subsequently inhibited the colony- and mammosphere-forming abilities of BCSCs and BCs." (PMID 36909163, 2023). "In this study, we identified 8 cDEGs (COL11A1, COL10A1, CD36, ACACB, CD24, PLK1, UBE2C, and PDK4) as breast cancer (BC)-causing HubGs from 3 microarrays and one scRNA-seq dataset by the protein-protein interaction (PPI) network analysis of 46 cDEGs." (PMID 37893423, 2023). "For example, a population of cells expressing CD44 high/CD24 low was identified as CSCs in breast cancer." (PMID 35464064, 2022). "To further support our data, we also characterized CD24−/CD44+ BCSCs from human luminal MCF-7 breast cancer cells." (PMID 35053617, 2022). "As breast cancer stem cells are characterized as CD44 + /CD24 − we trypsinized the MDA-MB-231 G85 and GNS spheres, stained them with CD44 and CD24 specific antibodies, and analyzed by flow cytometry." (PMID 35879327, 2022). "Recently, is has been revealed that ASCs are able to fuse spontaneously with breast cancer cells, where breast cancer stem cell (CSC) markers CD44+CD24−/lowEpCAM+ are enriched in this fused population." (PMID 36010901, 2022). "Further investigations into breast cancer have previously yielded fundamental marker discoveries including Mki67+ as a prognostic marker, Cd44+/Cd24+ as a breast cancer stem cell marker, and Trop2 as another therapeutic target." (PMID 36630696, 2022). "CD24 has potential as an immune therapy target in breast cancer, but further in vitro and in vivo studies are needed to clarify this." (PMID 35037689, 2022). "FGF13-AS1 was shown to interfere with glycolysis, OCT4 and SOX2 expression, spheroid formation and maintenance of CD44+CD24− population of breast cancer cells." (PMID 36429127, 2022).
breast cancer (continued). "For instance, a sub-set of breast cancer cells with CD44+/CD24−/low have a more aggressive phenotype, resulting in drug resistance and breast cancer metastasis." (PMID 35743249, 2022). "A study showed that endothelial cells co-cultured with breast cancer cells enriched the CD44 high CD24 low stem cell population in breast cancer cells." (PMID 36550571, 2022). "Our previous studies evaluated PTEN and pAkt protein and CD44/CD24 CSC marker expression in breast cancer tissues in the same cohort of African-American and Hispanic patients." (PMID 35053979, 2022). "Single-chain variable fragments (scFvs), selected from a total RNA library from lymphocytes of breast cancer patients, showed high selectivity for CD24 and CD44 and produced a synergistic effect when administered in combination with epirubicin." (PMID 36013184, 2022). "The presence of CD24 has been detected on several solid tumors and its importance in suppressing phagocytosis has recently been demonstrated in ovarian and breast cancer." (PMID 35688160, 2022). "At the same time, inhibition of Notch1 by specific antibodies significantly reduces the subpopulation of CSCs with the CD44+ CD24 phenotype and the frequency of brain metastases in breast cancer." (PMID 35563449, 2022). "Because it inhibited the PI3K/Akt/mTOR signaling pathway and has been proven to reduce breast cancer stem cells (CD44+/CD24), it was identified as a candidate for the treatment of breast cancer." (PMID 36233051, 2022). "Similar results were observed with CD24−/CD44+ BCSCs sorted from a human luminal breast cancer cell line, MCF-7." (PMID 35053617, 2022). "Several studies have reported that CD24 expression correlates with poor prognosis or metastasis in solid cancers such as ovarian cancer, breast cancer, prostate cancer, and lung cancer." (PMID 35289116, 2022). "In this study, the ESA+CD44+CD24− population of breast cancer, which has been widely used as a marker for breast cancer cells with stemness, was enriched in ReA cells as well as TSs." (PMID 36009455, 2022). "miR-31 was enriched in breast cancer stem cells (BCSCs) (CD24+CD90+) and an around 5-fold increase in comparison to CD24−CD90− was observed." (PMID 36429127, 2022). "Adipose-derived stem cells fused with breast cancer cells showed the enrichment of CD44 + CD24-/low EpCAM+ CSC marker expression in the fusion cell population." (PMID 36550571, 2022). "The cells were characterized using typical combinations of markers for breast cancer stem cells (CD24−, CD44+, ALDH1+)." (PMID 36077622, 2022). "We compared the PTEN, pAkt, and CD44/CD24 protein levels in breast cancer tissue determined by IHC with the serum levels of PD-L1." (PMID 35053979, 2022). "EpCAM, as well as the cancer-related protein CD24, has been detected on EVs isolated from ascites and pleural effusions from breast cancer patients." (PMID 35012489, 2022). "In breast cancer cells, CD24 expression has been shown to downregulate total and phosphorylated levels of STAT1." (PMID 36016357, 2022). "For breast cancer cells, IL-6/JAK/Stat3 signaling pathway is essential to maintain the CSCs property (CD44+CD24− cells), which suggested a prospective therapy mean to target the stem-like breast cancer cells." (PMID 36678534, 2022). "SSEA3 and SSEA1 (CD15) were detected in CD45−CD44+CD24− breast cancer stem cells, and brain tumor stem cells, respectively." (PMID 35883497, 2022). "Using a three-dimensional in vitro tumoral model we showed that the expression of lncMat2B, a lncRNA expressed in the hypoxic regions of multicellular tumor spheroids (MCTS), is increased in the CD44+/CD24- breast cancer cell subpopulation." (PMID 35626715, 2022). "Regulation of CD24 by miR34a, miR‐1185‐1, and miR146a has already been proposed in colon and breast cancer cells and oral squamous cell carcinomas." (PMID 34293822, 2022).
breast cancer (continued). "Limited CD24 expression in breast cancer cells was shown to augment their growth and metastatic potential through a chemokine receptor response." (PMID 36077806, 2022). "In the preclinical study, genetic ablation or antibody blockade of CD24 resulted in a macrophage-dependent reduction of ovarian and breast cancer growth." (PMID 36494785, 2022). "In another clinical trial, advanced breast cancer patients with a GSI MK-0752 treatment plus docetaxel have shown decreased CD44+CD24− and ALDH+ BCSC populations and lower mammosphere formation from their biopsies (NCT00106145, NCT00645333)." (PMID 35805056, 2022). "Clone SN3 promoted phagocytosis in ovarian and breast cancer patient-derived CD24+ cell lines, and it increased survival in vivo through the macrophage-mediated inhibition of tumor growth." (PMID 36013184, 2022). "The expression of Siglec-10 on TAMs from ovarian and breast cancer patients can be specifically combined with CD24 expressed on tumor cells." (PMID 35418152, 2022). "The potential of CD24 mAb treatment and checkpoint targeting was previously preclinically investigated for pancreas, ovarian, and breast carcinoma." (PMID 35625912, 2022). "More studies exhibit that CSCs are present in different solid tumors, including breast cancer, which is characterized by a CD24 −/CD44+ cell surface marker." (PMID 34947829, 2021). "Expression and localization of wild type N36- and/or N52-mutated CD24 were analyzed using immunofluorescence in luminal (MCF-7) and basal B (MDA-MB-231 and Hs578T) breast cancer cells lines, as well as HEK293T cells." (PMID 34360932, 2021). "The combination of CD44 and CD24 or aldehyde dehydrogenase 1 (ALDH1) is a representative cancer stem cell marker in breast cancer." (PMID 33861751, 2021). "It has been shown that inhibitors of this signalling pathway, such as quercetin and BEZ235 (dactolisib), decreased breast cancer ‘stemness’ via decreased expression of CD44+/CD24− phenotype." (PMID 34208799, 2021). "Our study shows, for the first time, the importance of N-glycosylation for the localization of CD24 at the cell periphery of breast cancer cells." (PMID 34360932, 2021). "It was shown that a high ratio of cells expressing CD44 to CD24 was correlated with strong tumorigenicity of breast cancer and ALDH was correlated with the metastatic capacity of the tumour." (PMID 34208799, 2021). "(F) Kaplan–Meier analysis of the DFS in the testing group of luminal breast cancer patients with endocrine therapy after they were stratified into ≥19.5% of CD44-/CD24- (n = 22) vs. <19.5% of CD44-/CD24- tumor cells (n = 19)." (PMID 34318746, 2021). "In the training set of patients, the metastasis rate in the patients with a high frequency (>19.5%) of CD44-/CD24- breast cancer cells was 1.97-fold higher than those with a low frequency (<19.5%) of CD44-/CD24- tumor cells." (PMID 34318746, 2021). "In breast cancer the expression and localization of CD24 was related to the different subtypes and the oncogenic properties of breast cancer cells." (PMID 34360932, 2021). "In this context, specific patterns of biomarkers that identify CSCs have been determined for some solid tumors such as CD44+CD24- for breast cancer." (PMID 33589595, 2021). "The current study aimed to explore the molecular mechanisms by which CD44-/CD24- cell conversion into CSC promotes delayed breast cancer metastasis." (PMID 34318746, 2021). "Time-dependent expression of ER-tag CD24 showed different kinetics for plasma membrane localization among the different breast cancer cell lines and HEK293T cells." (PMID 34360932, 2021). "CD44+/CD24- breast CSCs are crucial for the prognosis of breast cancer, but the potential prognostic values of CD44-/CD24- breast cancer cells are rarely studied." (PMID 34318746, 2021). "Identification of BCSCs from tumor samples and breast cancer cells relies mainly on CD44+/CD24– or ALDH phenotypes." (PMID 33763422, 2021).